CD4 (CD4 molecule)
Diseases named in the same sentence as CD4 in open-access papers (continued):
Sharing a sentence is not in itself a finding about the gene and the disease.
conjunctivitis (3 papers, 2008 to 2023). Inflammation of the conjunctiva of the eye. "Depletion of CD4+ T cells in our model revealed a complete dependency of conjunctivitis development following skin inflammation on this cell type, as evidenced by complete amelioration of ocular clinical scores." (PMID 36626228, 2023). "Here, we developed a potentially novel mouse model of skin inflammation–evoked conjunctivitis and showed that it is dependent on CD4+ T cells and basophils." (PMID 36626228, 2023). "We demonstrated that basophils and CD4+ T cells were required for the development of conjunctivitis in mice, as depleting them following the sensitization phase limited the disease." (PMID 36626228, 2023). "The role of CD4+ T cells in experimental conjunctivitis was assessed in mice treated with a depleting anti-CD4 Ab (GK1.5) 6 days prior to ocular OVA challenge and again on the day of challenge." (PMID 36626228, 2023). "For example, when mast cell degranulation is induced in the conjunctiva by compound 48/80, the resulting conjunctivitis is characterized by infiltration of neutrophils, macrophages, and CD4+ T lymphocytes but surprisingly few eosinophils." (PMID 18728750, 2008). "Central to the pathogenesis of allergic disorders and conjunctivitis are CD4+ T cells." (PMID 36626228, 2023). "CD4+ T cells mediate antigen-specific skin inflammation–evoked conjunctivitis development." (PMID 36626228, 2023).
corneal infection (3 papers, 2011 to 2024). A viral or bacterial infectious process affecting the cornea. "Corneal infection caused an influx of primarily CD4+ T cells into the TG of immunized mice compared with naïve controls (P<0.05 to 0.001)." (PMID 21826207, 2011).
coronary artery aneurysms (3 papers, 2020 to 2025). "Later, CD8+ lymphocytes, much more than CD4+ lymphocytes, with macrophages predominantly appears at the time of coronary aneurysm formation." (PMID 38451335, 2024). "However, in this report, we present 2 KD children with sustained coronary artery aneurysms (CAA), and we found that their peripheral C-X-C Chemokine Receptor 5+ T cells contained quite amounts of CD4 negative cells." (PMID 33350751, 2020).
coronary artery stenosis (3 papers, 2013 to 2024). "The study revealed that a combination of IL-6, IL-10, and CD4 + T lymphocytes outperformed individual biomarkers in predicting functional coronary artery stenosis." (PMID 38443781, 2024). "Furthermore, the combination of IL-6, IL-10, and CD4+ T lymphocytes is a better predictor of functional coronary stenosis than any single biomarker." (PMID 34660716, 2021).
cryopyrin-associated periodic syndrome (3 papers, 2017 to 2018). Cryopyrin associated periodic syndrome (CAPS) defines a group of autoinflammatory diseases, characterized by recurrent episodes of systemic inflammatory attacks in the absence of infection or autoimmune disease. "Aligning with a key role for the NLRP3 inflammasome in sustaining the human Th1 response, CD4+ T cells from patients that suffer from cryopyrin-associated periodic syndromes (CAPS) due to gain-of-function mutations in NLRP3, display also significantly increased IFN-γ production." (PMID 30305631, 2018).
ductal adenocarcinomas (3 papers, 2020 to 2026). "Single-cell RNA sequencing (scRNAseq) of an ER+/HER2 + invasive ductal carcinoma sample further confirmed that BRRIAR expression was largely restricted to tumor cells (16.5%), with only sparse expression detected in platelets (5.5%), CD4+/CD8 + T-cells (3.8%), and other cell types." (PMID 41501810, 2026).
dysgammaglobulinemia (3 papers, 2021 to 2025). An immunologic deficiency state characterized by selective deficiencies of one or more, but not all, classes of immunoglobulins. "The hallmark laboratory findings are dysgammaglobulinemia, particularly elevated IgM, and normal to low IgG, together with high transitional B cells, and low naïve CD4 and CD8 T cells." (PMID 34350147, 2021). "The APDS type 2 patient identified through this screening also exhibited dysgammaglobulinemia, impaired antibody responses to antigens, and an inverted CD4+/CD8+ ratio." (PMID 41583441, 2025). "Recurrent URTI, lymphoproliferation, dysgammaglobulinemia, impaired antibody response to antigens, inverted CD4+/CD8+ ratio." (PMID 41583441, 2025). "Based on these immunological features, our screening strategy defined major criteria as dysgammaglobulinemia, decreased CD19+ B cells/decreased CD19+CD27+IgM-IgD- cells, an inverted CD4+/CD8+ T cell ratio, and increased CD8+CD45RA+CD27+ cells." (PMID 41583441, 2025).
endometrial tumors (3 papers, 2022 to 2025). "To analyze whether and how CC-3 induced T cell proliferation, we labeled PBMCs of healthy donors using CellTraceTM Violet and analyzed CD4+ and CD8+ T cell counts in cocultures with endometrial tumor cells upon exposure to CC-3 or control by flow cytometry." (PMID 40707958, 2025). "CD8+ T cells, CD20+ B cells, CD4+ T cells, and CD38+ PCs were common in endometrial tumors." (PMID 34689225, 2022).
endophthalmitis (3 papers, 2012 to 2024). An infectious process affecting the internal structures of the eye. "Notably, none of the patients in our analysis developed endophthalmitis, despite having low CD4 counts, suggesting that CD4 levels may not serve as a reliable predictor of postoperative infections." (PMID 39588421, 2024).
epidermolysis bullosa acquisita (3 papers, 2021 to 2024). "More recent experimental evidence in a mouse model of epidermolysis bullosa acquisita would confirm the immunomodulatory role of vitamin D via increase of CD4+ forkhead box P3 (FoxP3)+ Tregs and B cells (CD19 + IL10+), concomitant with the reduction of proinflammatory Th17 cells." (PMID 39796035, 2024). "Similarly, calcitriol increased the percentage of Tregs (CD4+ FoxP3+) and Bregs (CD19+ IL-10+) and reduced proinflammatory Th17 (CD4+ IL-17+) cells in mice with immunization-induced epidermolysis bullosa acquisita." (PMID 38201878, 2023).
Familial adenomatous polyposis (3 papers, 2019 to 2022). Familial adenomatous polyposis (FAP) is characterized by the development of hundreds to thousands of adenomas in the rectum and colon during the second decade of life. "In mouse C57BL/6J-Min/+, bearing a germline Apc mutation, a classical model of familial adenomatous polyposis (FAP) and sporadic colorectal cancer, administration of curcumin increases mucosal CD4+ T and B cells and contributes to prevent adenoma formation." (PMID 31031748, 2019).
Fasciola hepatica infection (3 papers, 2021 to 2025). "This elevation can benefit the host during Fasciola infection by reducing IL-10 production by specific CD4+ T cells and enhancing eosinophil degranulation triggered by specific antibodies." (PMID 40864124, 2025). "Altogether, these results suggest that HO-1 activity inhibited by SnPP decreases the production of ROS/RNS during fasciolosis and correlates with an increase of splenic regulatory CD4+ T cells in a process that might involve ICOSL in antigen-presenting cells or CTLA4 expression in Tregs." (PMID 34943041, 2021). "Filarial lymphedema in humans correlates with an exhausted phenotype in both CD4 and CD8 T cells, and increased levels of exhausted CD4+ T cells are seen in chronic bovine Fasciola hepatica infection." (PMID 40755147, 2025).
female infertility (3 papers, 2019 to 2022). Diminished or absent ability of a female to achieve conception. "Recently, tacrolimus has also been used to treat female infertility and prevent adverse pregnancy outcomes in women with recurrent pregnancy loss with elevated systemic Th1 (CD4+ IFNγ+): Th2 (CD4+IL4+) cell ratios." (PMID 35955565, 2022).
fibromyalgia (3 papers, 2020 to 2025). A chronic disorder of unknown etiology characterized by pain, stiffness, and tenderness in the muscles of neck, shoulders, back, hips, arms, and legs. "Human studies in fibromyalgia have demonstrated increased Th1 type signature of CD4+ T cell subpopulations, with associated increases in interferon-gamma (IFNγ) and TNFα production and correlation with disease severity." (PMID 40002538, 2025). "This suggests that there are no clear differences in the activation state of CD4+ T cells in patients expressing the different allelic variants, but there is a general increase in CD4+ T cells expressing intermediate or late activation markers in patients with fibromyalgia." (PMID 32054062, 2020). "In a cohort of 36 patients, analysis of the circulating CD4+ T cell subsets showed an increased Th1 type signature in fibromyalgia patients compared to controls." (PMID 32054062, 2020). "Overall the concept that mainly emerges from the analysis of the results of these studies is an increase in the function and percentage of CD4+ T cells with a Th1 signature in fibromyalgia patients." (PMID 32054062, 2020). "The results indicated that the number of CD3+T cells expressing the activation markers CD69 and CD25 was decreased in patients with fibromyalgia, whereas the CD4/CD8 ratio was similar in patients and controls." (PMID 32054062, 2020). "Together, these results indicate the expansion of Th1 cell subpopulations and a general trend toward higher levels of inflammatory cytokine-producing CD4+ cells in subjects with fibromyalgia compared with those with unrelated diseases." (PMID 32054062, 2020). "CD4+ T cells from patients required a higher concentration of the mitogen concanavalin A in order to reach optimal secretion of IL-2, thus indicating a lower response of CD4+ T cells from fibromyalgia patients to activating stimuli." (PMID 32054062, 2020). "A subsequent study was performed on 65 patients with fibromyalgia, and lymphocyte subpopulations were analyzed, including CD3+T cells, CD19 (B cells), CD16 (natural killer cells), CD4+ T helper, and CD8+ cytotoxic T cells." (PMID 32054062, 2020). "Another study found reductions in cytotoxic CD8+ T cells in fibromyalgia and CRPS patients that correlated with post-traumatic stress scores without alterations in CD4/CD8 ratio, again suggesting a connection between pain, stress, and lymphocyte populations." (PMID 40002538, 2025).
folate deficiency (3 papers, 2010 to 2020). A nutritional condition produced by a deficiency of FOLIC ACID in the diet. "Folate deficiency has also been associated with reduced T-cell proliferation in response to mitogen activation, lowered resistance to infections, and increased CD4:CD8 T-cell ratios." (PMID 27387046, 2016). "Pregnant women with gastrointestinal symptoms and CD4 count <350 were seven times more likely to have folate deficiency (odds ratio [OR] 7.8, 95% confidence interval [CI] 1.6–38.1; p = 0.009) and six times more likely to have poor zinc intake (OR 6.7, 95% CI 1.3–36.8; p = 0.014)." (PMID 32442181, 2020).
Fulminant hepatitis (3 papers, 2011 to 2024). Acute hepatitis complicated by acute liver failure with hepatic encephalopathy occurring less than 8 weeks after the onset of jaundice. "The immunological helper/suppressor (CD4+/CD8+) ratio of fulminant hepatitis was significantly lower compared to acute cases." (PMID 21605420, 2011).
Gaucher disease (3 papers, 2019 to 2025). Gaucher disease (GD) is a lysosomal storage disorder encompassing three main forms (types 1, 2 and 3), a fetal form and a variant with cardiac involvement (Gaucher disease - ophthalmoplegia - cardiovascular calcification or Gaucher-like disease). "Future research should therefore focus on pro-inflammatory immune cells, such as macrophages, CD4 T helper cells, and mast cells, to better elucidate the mechanisms underlying secondary HLH-like symptoms in patients with Gaucher disease." (PMID 41181118, 2025). "However for Fabry disease patients, an alteration in the frequency of CD4/CD8/DN iNKT cells was observed in Gaucher disease patients, showing a significant increase of the CD4+ population and a decrease of DN and CD8+ iNKT cells." (PMID 31214199, 2019). "Here, we delineate role of the CXCR3 receptor and its exogenous C-X-C motif chemokine ligand 9 (CXCL9) in induction of increased tissue recruitment of CD4+ T and CD8+ T cells in Gaucher disease." (PMID 34884512, 2021). "However, when CD4/CD8 expression was analyzed, Gaucher disease patients showed an increase in the percentage of CD4+ and a decrease in the percentage of DN and CD8+ iNKT cells." (PMID 31214199, 2019).
Genital ulcers (3 papers, 2011 to 2017). "Genital ulcers can facilitate HIV transmission by breaching protective mucosal barriers and recruiting susceptible immune cells (e.g., CD4 T-helper cells, macrophages) to the site of infection, and can also create portals of entry for HIV to access susceptible cells." (PMID 28003032, 2016). "HSV-2-seropositive women with genital ulcers may differ from co-infected women with asymptomatic HSV-2; and this difference cannot be explained by CD4 count alone." (PMID 21637835, 2011).
haemophagocytic syndrome (3 papers, 2016 to 2021). "SFTS patients are somewhat immunodeficient or have damaged immune systems with low levels of CD3+ and CD4+ T lymphocytes, which may be due to a viral-associated hemophagocytic syndrome." (PMID 28153057, 2017).
Hematochezia (3 papers, 2018 to 2022). The passage of fresh (red) blood per anus, usually in or with stools. "A 48-year-old man with HIV infection (CD4 count = 84 cells/μL) presented with hematemesis and hematochezia." (PMID 35469209, 2022). "A 48-year-old man with HIV infection (CD4 count = 84 cells/μL) experienced hematemesis and hematochezia." (PMID 35469209, 2022).
hematoma (3 papers, 2019 to 2022). A hematoma is a collection of blood from a vascular structure into an extravascular space. "The number of CD4+ CD25+ cells in peri-hematoma tissue gradually increased from the 1st day, and this trend was maintained until 7 days after ICH." (PMID 36435797, 2022). "In contrast, absence of sympathetic nerve fibers strongly reduced the number of hematoma-derived CD4-positive helper T-cells and CD8-positive cytotoxic T-cells 5 days after fracture." (PMID 31936403, 2020). "Remarkably, this imbalance of CD8+ TEFF/CD4+ TReg was also reflected in the facture hematoma." (PMID 31475013, 2019).
hemorrhagic stroke (3 papers, 2013 to 2023). A stroke caused by a bleed on the brain. "Reduced blood CD4+ T-cell counts among patients who had severe hemorrhagic stroke increased the risk of early infection." (PMID 37360336, 2023). "The migration of CD4+ T cells into the brain exacerbates neuroinflammation in the central nervous system and is involved in the secondary damage caused by hemorrhagic stroke." (PMID 37360336, 2023). "In conclusion, we found that the decline in CD4+ T-cell levels in the blood after the onset of severe hemorrhagic stroke leads to an increased risk of early infection." (PMID 37360336, 2023). "The median CD4+ T-cell count in 126 patients with severe hemorrhagic stroke was 308.41/μL (IQR 206.79/μL–485.83/μL), which was less than the normal range (550–1,440/μL)." (PMID 37360336, 2023). "Another experimental work showed that the elevated number of CD4+ T lymphocytes appeared 4 days after induction of hemorrhagic stroke." (PMID 31514749, 2019). "According to the findings of this study, the decrease in blood CD4+ T-cell levels and the occurrence of consciousness disorder in patients who had severe hemorrhagic stroke during the acute phase had obvious predictive value for the occurrence of early infection." (PMID 37360336, 2023). "CD4+ T cells in CSF may originate from CD4+ T-cell migration from the blood, which may be one of the reasons for the reduction in blood CD4+ T-cell levels in patients with severe hemorrhagic stroke." (PMID 37360336, 2023). "Moreover, CD4+ T cells can access sites of inflammation in the central nervous system due to cytokine chemotaxis, which may be relevant to the pathological mechanisms of hemorrhagic stroke." (PMID 37360336, 2023). "Another type of leukocytes contributing to the immune response after hemorrhagic stroke is CD8+ T cells and CD4+ T cells." (PMID 31514749, 2019).
herpes simplex (3 papers, 2004 to 2026). "The CD4 cell count must be taken into account in the treatment of herpes simplex." (PMID 21739017, 2011).
hip fracture (3 papers, 2014 to 2021). Traumatic or pathological injury to the hip in which the continuity of either the femoral head, femoral neck, intertrochanteric or subtrochanteric regions is broken. "On examining cytokine production by activated T cells, a significant increase in TNFα (p = .03) and IL6 (p = .04) production was observed in CD4 T cells from hip fracture patients with depressive symptoms compared to healthy controls." (PMID 25628751, 2014). "However, significant differences occurred in absolute numbers of CD4 T cells, F = 6.01, p = .004, η2 = .18, driven by a significant decline in absolute numbers of CD4 T cells in hip fracture patients with depressive symptoms compared with healthy controls (p = .006) only." (PMID 25628751, 2014). "In conclusion, the present study reports for the first time that development of new onset depressive symptoms in older hip fracture patients results in numerical and functional deficits in Bregs but an increase in IL10 production by CD4 T cells." (PMID 26112234, 2016). "On examining CD57 expression, we found significant differences in CD57+ve CD4 T cells, F = 1.32, p = .008, η2 = .16 between the three groups, driven by an increase in the percentage of CD57+ve T cells in hip fracture patients with depressive symptoms compared with healthy controls (p = .003)." (PMID 25628751, 2014). "Interestingly, there was a significant association between GDS scores and the frequency of peripheral IL10+ CD4 T cells in hip fracture patients, β = .34, p = .04, ΔR2 = .11, such that hip fracture patients with greater depressive symptoms (GDS score) had a higher frequency of IL10+ CD4 T cells." (PMID 26112234, 2016). "Thus, the naïve:memory ratio for CD4 T cells also did not significantly differ between hip fracture patients with and without depressive symptoms and healthy controls, F = .21, p = .80, η2 = .005." (PMID 25628751, 2014). "However, in this study no such increase in Th17 producing CD4 T cells was observed in hip fracture patients with depressive symptoms post stimulation." (PMID 25628751, 2014).
HIV enteropathy (3 papers, 2014 to 2019). A syndrome characterized by chronic, well-established diarrhea (greater than one month in duration) without an identified infectious cause after thorough evaluation, in an hiv-positive individual. "HIV enteropathy may cause disruption of the intestinal barrier, leading to a loss of CD4+ T cells, increased intestinal permeability, and microbial translocation." (PMID 31341568, 2019). "Possible explanations for these results are inflammation of the small intestine found at low CD4 levels (HIV enteropathy) with activation of the immune system and release of inflammatory mediators, contributing to elevation of angiotensin II and salt accumulation." (PMID 29623220, 2018).
human papillomavirus infection (3 papers, 2022 to 2025). "This cluster is primarily involved in regulating ECM-receptor interaction, focal adhesion, PI3K-Akt signaling pathway and human papillomavirus infection signaling pathway, and correlated strongly with higher infiltration of CD4+ T cells, macrophages, neutrophils, and dendritic cells." (PMID 36249004, 2022). "The upregulated pathways in CD4+ TEM cells included ribosome biogenesis, coronavirus infection, human papillomavirus infection, mitogen-activated protein kinase (MAPK) signaling, and PI3K-Akt signaling, implicating these cells in active protein synthesis and immune responses." (PMID 41246350, 2025).